MYCN (MYCN proto-oncogene, bHLH transcription factor)
Diseases named in the same sentence as MYCN in open-access papers (continued):
Sharing a sentence is not in itself a finding about the gene and the disease.
tumor (continued). "We found that an extra-abdominal primary site, lower stage (stage 1/2), MYCN non-amplified tumor, and low-risk group categorization were associated with a longer germline telomere length (P = 0.015, 0.007, 0.046, and 0.042, respectively)." (PMID 35902621, 2022). "We investigated 792 and 1154 in an in vivo murine model and found that tumor growth was significantly decreased in both MYCN amplified and non-amplified tumors following treatment with 792, but 1154 significantly decreased tumor growth in only the MYCN amplified tumors." (PMID 35454859, 2022). "BGA002 showed a specific, dose-dependent decrease in the MYCN mRNA and protein, while decreasing the viability in a panel of 20 NB cell lines, followed by the block of different MYCN tumorigenic alterations, and to the anti-tumor efficacy of BGA002 in vivo in a MNA NB mouse model." (PMID 35890348, 2022). "Cells expressing MYCN could be grown in vitro and, when orthotopically injected, formed tumours that infiltrated the sclera and optic nerve and expressed markers for cone progenitors." (PMID 35729105, 2022). "More importantly, only tumors treated with DZNep exhibited MYCN (and EZH2) loss even though 50 mg/kg of GSK126 was as capable as 3 mg/kg of DZNep in diminishing H3K27me3 expression within tumor cells (compare the H3K27me3 immunochemistry images between GSK126 and DZNep treatment)." (PMID 35013218, 2022). "Molecular tumor tissue analysis detected neither MYCN nor ALK copy-number alterations nor ALK hotspot mutations." (PMID 35565208, 2022). "In all three tumor models, MYCMI-7 treatment led to reduced MYC or MYCN expression in tumor tissue." (PMID 36874405, 2022). "Alternative modes of NB initiation and progression may involve the de-differentiation of normal, precancerous, and tumor cells, especially in MYCN-amplified NBs." (PMID 35277192, 2022). "The presence of IDRFs can predict the extent of the surgery, and it should be integrated as part of the treatment plan, but it is probably best used in association with other prognosis factors, such as MYCN amplification, NSE level, tumor size, and histological characteristics." (PMID 36360435, 2022). "To test dependence of EIF4EBP1 expression as prognostic factor on established factors of poor prognosis, we performed multivariate analysis to determine the statistical interaction between high EIF4EBP1 expression and MYCN amplification status, tumor stage or age at diagnosis." (PMID 35379801, 2022). "Tumor samples from high-risk NB patients with and without MYCN amplification show the expression of canonical Wnt pathway target genes at high levels, indicative of Wnt pathway deregulation in NB." (PMID 36428626, 2022). "Mechanistically, we found that SOX11 is a direct target of miR-145-5p, which might mediate miR-145-5p’s tumor-suppressive functions by regulating MYCN during NED of PCa cells." (PMID 35368699, 2022). "Thirty-five patients underwent MYCN amplification test on tumor specimens." (PMID 35359419, 2022). "BET and CDK-7 inhibition display selective effects on MYCN-amplified tumor cells, which may be explained by preferentially targeting super-enhancer driven transcription." (PMID 35681734, 2022). "However, with a deeper understanding of MYCN, we have found that MYCN plays an important role in many fields of tumor microenvironment." (PMID 36311753, 2022).
tumor (continued). "In addition to the INSS, NB patients can be stratified into low, intermediate, and high-risk disease groups depending on the age at diagnosis, stage, histology, MYCN status, and tumor cell ploidy." (PMID 36139358, 2022). "Overexpression of MYCN mRNA in MYCN-amplified NB has an independent function promoting NB cell proliferation through inhibiting the tumor suppressor miRNA let-7: the 3’UTR of MYCN mRNA has multiple binding sites for let-7, and binding of let-7 to MYCN 3’UTR can inhibit let-7 activity." (PMID 36505784, 2022). "MYCN promotes various metabolic adaptations to support tumor growth." (PMID 35764645, 2022). "Existing clinical studies have shown that tumour cells rely more than normal cells on a high level of SE-driven transcriptional regulation mediated by specific oncogenes, such as RUNX1 (encoding RUNX family transcription factor 1) in AML and MYCN in NB." (PMID 35303940, 2022). "Furthermore, strong reduction in MYCN expression was observed in tumor cells by IHC, again indicating the MYCMI-7 had reached its target in tissues." (PMID 36874405, 2022). "A MYCN-dependent oncogenic pathway plays a key role in promoting the aggressive, intrinsically resistant disease phenotype, in part by modulating the expression of ATP-binding cassette transporters driving active efflux of chemotherapeutics from tumor cells." (PMID 35163672, 2022). "In addition, the hematogenous metastases of tumor cells to the similar common sites of metastases seen in patients were also observed in the transgenic fish lines with overexpression of MYCN and LMO1 or LIN28B." (PMID 33800887, 2021). "However, SR1078 was not able to block tumor growth in a non-MNA xenograft model of SK-N-AS cells (p = 0.5116), suggesting that the tumor-suppressive function of RORα activation is MYCN-dependent." (PMID 34183658, 2021). "Inhibitors that downregulate MYCN/MYC proteins can suppress N.B. tumor growth." (PMID 34943600, 2021). "For example, Lodrini and collogues reported lower MYCN copy numbers in cfDNA than matched tumor DNA which could be attributed to dilution effect from damaged white blood cells arising from suboptimal pre-analytic handling of the blood samples." (PMID 34282791, 2021). "However, inhibition of one pathway alone will often result in minor to moderate anti-tumor activity, suggesting concurrent targeting of MYCN transcription and mTOR signaling is important strategy to enhance efficacy." (PMID 34565342, 2021). "Model systems such as patient-derived iPSCs, and human hindbrain-derived neuroepithelial stem cells align with the developmental trajectory of the CNS, therefore are likely to reflect a more authentic evolution of the tumour through targeting of relevant oncogenes such as MYCN." (PMID 34195095, 2021). "Although we cannot report on the autopsy of 5 out of 25 animals, we assume that a simultaneous loss of Brg1 and overexpression of MYCN in Math1 positive GNPCs is not sufficient to drive tumor growth." (PMID 33387268, 2021). "Understanding how major oncogenic drivers such as MYCN activate and bypass such pathways during tumor initiation offers insights that may be of use for development of novel therapeutic strategies." (PMID 34262099, 2021). "FISH analysis of some of these cases could also confirm that amplified MYCN and ultra-bright telomere spots are present in the same tumor." (PMID 33627664, 2021). "Tumor infiltration of adjacent organs and structures was associated with decreased survival (HR = 8.90, p = 0.007), increased risk of INSS stage 4 disease (OR = 8.96, p < 0.001), MYCN amplification (OR = 9.91, p = 0.001), and high MKI (OR = 6.20, p = 0.003)." (PMID 33314708, 2021). "Importantly, high ALYREF mRNA expression strongly correlated with MYCN expression in ganglia tissues throughout tumor progression." (PMID 33767157, 2021).
tumor (continued). "Interestingly, we noticed that the expression of SLC40A1, which encodes the only known iron exporter ferroportin, is slightly but reproductively reduced upon MYCN overexpression, and RNA-seq analysis of NB tumor tissues also supports this argument." (PMID 34011924, 2021). "Using Ki67 as a marker for cell proliferation, we noted significantly increased reactivity in Alk‐F1178S;Th‐MYCN, compared with Th‐MYCN tumours, suggesting that the increased potential for tumour development is initiated at early stages in the sympathetic ganglia of animals bearing both oncogenes." (PMID 33411331, 2021). "Focal MYCN amplification was present in four eyes (6.3%; Cases 3, 10, 31, and 48); the presence of MYCN amplification does not necessarily denote a MYCN-driven tumor which clearly Case 10 is not (germline RB1 mutation present)." (PMID 34283049, 2021). "Moreover, aggressive Alk/MYCN-driven mouse NB tumour models respond completely and maintain a long-term tumour-free response." (PMID 34819497, 2021). "MYCN amplifications are the most common somatic mutations in NBL and are correlated with chromosome 17q gain, tumour invasiveness, progressive disease, and tumour metastasis." (PMID 34575503, 2021). "miR-628-3p has a tumor-suppressor characteristic and down-regulates MYCN." (PMID 33718173, 2021). "Two papers recently highlighted the importance of other potential driver mutations including focal MYCN amplification, first reported in 1–2 % of tumours with no detectable RB1 mutations." (PMID 33670346, 2021). "Even though the postnatal loss of Brg1 alone appeared to show a trend towards enhanced proliferation, the combination of MYCN overexpression and Brg1 loss did not synergize and did still not result in tumor formation." (PMID 33387268, 2021). "We identified two examples of Rb tumours with both biallelic RB1 mutations and MYCN amplification." (PMID 33670346, 2021). "Transcriptional profiling of such a large cohort of a single molecular type of cancer allows for a thorough understanding of the tumor’s genomic landscape, including the identification of genes affected by mutations (GNAS, MYCN, PPM1D, and PRKAR1A), and fusion transcripts (ZBTB20 and NCOR1)." (PMID 33741928, 2021). "Combining Alk‐F1178S with Th‐MYCN resulted in a significant increase in the aggressiveness of tumour development, exemplified by complete tumour penetrance at 30 wk together with markedly earlier tumour onset, averaging 8 wk." (PMID 33411331, 2021). "However, genes contributing to tumor growth and aggressiveness of NB under MYCN regulation still remain elusive." (PMID 34277416, 2021). "In addition to MYCN amplification status, tumor stage and age are also important prognostic variables that are considered during risk stratification." (PMID 34458583, 2021). "Additionally, is also associated with advanced stage disease, an overall poor prognosis, and therapy resistance, with MYCN-amplified tumours being resistant to current therapeutic approaches." (PMID 33968920, 2021). "Because BRCA1 is highly expressed in neuronal progenitor cells during early development and MYC is less efficient than MYCN in recruiting BRCA1, the Eilers team suggests that a cell-lineage-specific stress response enables MYCN-driven tumours to cope with deregulated RNAPII function." (PMID 34945759, 2021). "Moreover, TFRC overexpression phenocopies MYCN amplification to increase the intracellular iron pool and sensitize these tumor cells to ferroptosis." (PMID 34011924, 2021). "To investigate whether ALKAL2‐driven NB is sensitive to ALK TKI treatment, we first established murine NB cell lines from tumours harvested from Rosa26_Alkal2;Th‐MYCN and Alk‐F1178S;Th‐MYCN mice." (PMID 33411331, 2021). "The relationship of MYCN with the tumour immune microenvironment has only begun to be explored." (PMID 34884690, 2021).
tumor (continued). "In this study, we demonstrate that the combination of a Brg1 deficiency with MYCN amplification in mice is not sufficient to drive tumor formation, neither in postnatal Math1 expressing cells nor in hGFAP positive multipotent NSCs." (PMID 33387268, 2021). "The response to OTX105 differs in tumor types encompassing mechanisms that include suppression of cell proliferation and viability, downregulation of MYC/MYCN proteins and MYC-regulated transcriptional programs, loss of stemness features and chromatin remodeling." (PMID 33668642, 2021). "Furthermore, a zebrafish MYCN/RRM2 co-overexpression model revealed a strong increase in tumor penetrance compared to MYCN only overexpressing animals." (PMID 34945759, 2021). "Since the first experiments using ectopic MYCN expression in cell lines and targeted MYCN overexpression in peripheral NC transgenic NB mouse model, strong evidence that increased MYCN activity is involved in tumor initiation and progression of NB has been provided." (PMID 34771690, 2021). "However, MYCN overexpression also results in a vulnerability called transcriptional addiction and creates tumor-selective gene dependencies, which include the adrenergic CRC transcription factors that sustain high levels of MYCN gene expression." (PMID 34669465, 2021). "In comparison, the MYCN locus was present at a 2-copy state with two signals detected for both MYCN and the centromere of chromosome 2 (primary tumor: nuc ish(MYCNx2)[89/100]), recurrent tumor: nuc ish(MYC amp)[87/100])." (PMID 34895332, 2021). "The BrdU experiment showed that telomerase activity declined early and progressively during the conversion of ADRN cells into MES cells, suggesting that this activity may be involved in NB tumor cell differentiation, especially in MYCN-amplified tumor cells." (PMID 34799676, 2021). "The risk of death for each NB patient is defined based on disease presentation, age at diagnosis, tumor histology, tumor ploidy, localized or metastatic disease, recurrent segmental chromosome copy number alterations, and amplification of the proto-oncogene MYCN." (PMID 34072462, 2021). "MYCN amplification is an independent poor prognosis marker for many tumor types." (PMID 34508175, 2021). "In addition, the let-7 miRNA family, a group of well-known tumor-suppressing miRNAs, is a repressor of MYCN and can be repressed by LIN28B." (PMID 35008302, 2021). "Thus, MYCN inhibition can be a potential therapeutic strategy in combination with existing chemotherapy drugs to restrict tumor cell growth in RB." (PMID 34680394, 2021). "Similarly, the inferred SHH-MB tumor purity was correlated with MYCN expression (r = 0.2961, p = 0.04572) and anticorrelated with let-7 activity (r = −0.3261, p = 0.0270)." (PMID 35008302, 2021). "Overall, our data suggests that targeting MYCN may limit tumor cell migration in RB possibly via downregulating the expression of ECM proteins and VEGFA." (PMID 34680394, 2021). "In this regard, it is possible that inhibiting telomerase in MYCN-amplified tumors may prove especially efficacious—by simultaneously eliminating telomere maintenance and enhancing immunogenicity through tumor cell lineage reprogramming." (PMID 34799676, 2021). "Thus, the association between the TI-signature and MYC/MYCL/MYCN amplification status were examined and the results indicated that the TI-signature score represented the MYC pathway in the tumor cells." (PMID 34122516, 2021). "We postulated that the co-amplifications of genes located on chromosome 2p could functionally cooperate with MYCN amplification increasing NB cell proliferation and tumor aggressiveness." (PMID 34830942, 2021). "MYC family genes also regulate transcription via epigenetic modifications, suggesting that epigenetic drugs could be used in the clinic to successfully treat MYC/MYCN-amplified tumours." (PMID 34195095, 2021).
tumor (continued). "Taken together, analysis of Th‐MYCN, Alk‐F1178S;Th‐MYCN and Rosa26_Alkal2;Th‐MYCN mice revealed a high level of tumour penetrance in both Alk‐F1178S;Th‐MYCN (98% at 200 days) and Rosa26_Alkal2;Th‐MYCN (89% at 200 days), relative to that observed in Th‐MYCN mice (46% at 200 days)." (PMID 33411331, 2021). "Observations made with BET inhibitors JQ1 or OTX015 targeting both c-MYC and MYCN warrant additional studies using MYCN specific inhibition such as HUWE1 inhibitors or specific knockdown to differentiate the relative importance of c-MYC and MYCN in ATL tumor cells survival and proliferation." (PMID 32907612, 2020). "Despite the extensive study of the genomic characteristics of high-risk NB including MYCN-amplified tumours, genomic profiling of MYCN non-amplified NB, including low- and intermediate-risk NB, has been limited." (PMID 33172452, 2020). "Furthermore, its contribution is effectively increased in those tumours also carrying the amplification of the MYCN proto-oncogene." (PMID 33168834, 2020). "By comparing the clinical characteristics between non-ruptured (n = 93) and ruptured (n = 40) high-risk NB, we found significant differences in age, primary site, maximum diameter of the primary tumor, tumor marker levels, pathological characteristics, and the MYCN gene (P < 0.05)." (PMID 32293329, 2020). "In our study, the most concern is whether plasma MYCN/NAGK ratio could evaluate amplified MYCN of NB tumor accurately." (PMID 32896084, 2020). "Similarly, it was shown that depletion of MycN in tumor-derived neurosphere cell line, derived from a GEM model of MycN-driven MB, negatively affects the expansion of cells expressing markers of NSCs and/or progenitors associated with MB tumorigenesis." (PMID 32528946, 2020). "MYCN-amplified tumours make up about 40% of high-risk NBs, indicating that 60% of high-risk NBs are MYCN non-amplified tumours." (PMID 33172452, 2020). "We then examined MYCN status regarding gene copy number and expression in these tumor tissues." (PMID 33270844, 2020). "We propose that MYCN gene expression might represent a potential predictive biomarker of tumor stemness and plasticity." (PMID 33937011, 2020). "For instance, CRISPR‐mediated depletion of MYCL or MYCN in mouse tumor‐derived SCLC could reduce tumor formation capacity, but MYC could not." (PMID 32281704, 2020). "Furthermore, in post-hoc exploratory analyses, nine (82%) of 11 patients with distantly relapsed diffuse MBSHH tumours had MYCN amplification at diagnosis, compared with two [25%] of eight patients with nodular MBSHH relapses (p=0·024)." (PMID 33222802, 2020). "MYCN examined by fluorescence in situ hybridization (FISH) was amplified in 2.6% of tumor cells." (PMID 33019449, 2020). "In the Th-MYCN mouse model, tumor penetrance is only high in a 129 x 1/SvJ strain background." (PMID 33585251, 2020). "We could also see that expression of DLG2 was inversely correlated with MYCN status and tumor stage." (PMID 32312269, 2020). "Finally, transplanting miR‐15a‐, miR‐15b‐ and miR‐16‐expressing NB cells into NSG mice repressed tumor formation and MYCN expression." (PMID 31637848, 2020). "Then, we examined the MYCN expression in a three-dimensional (3D) multicellular tumor spheroid system, which could mimic in vivo 3D tumor growth and promote stemness maintenance." (PMID 31988297, 2020). "This feature might become of clinical relevance as it has been shown that the inhibition of β-oxidation induces differentiation in MYCN expressing tumor spheroids and leads to a decreased tumor growth in MYCN amplified cell lines when injected into nude mice." (PMID 33585251, 2020).